ENTPD8 (ectonucleoside triphosphate diphosphohydrolase 8)
Description:
Canalicular ectonucleoside NTPDase responsible for the main hepatic NTPDase activity. Catalyzes the hydrolysis of nucleoside triphosphates (NTPs) and diphosphates (NDPs). The enzyme sequentially removes phosphate groups in two successive steps, converting NTPs to nucleoside monophosphates (NMPs) via NDP intermediates. This activity contributes to the regulation of extracellular levels of nucleotides. Hydrolyzes ATP, UTP, ADP, and UDP and prefers triphosphonucleosides and adenine over uracil as substrates. Does not hydrolyzes AMP.
Synonyms: UNQ2492; NTPDase-8; E-NTPDase; GLSR2492
Tractability: Antibody: its Gene Ontology location is reachable by antibodies, with high confidence; UniProt places it where antibodies can reach, with medium confidence; UniProt predicts a signal peptide or a membrane-spanning region.
Target class: Enzyme; Hydrolase
Gene: Protein-coding gene on chromosome 9 (137,434,362 to 137,441,881, reverse strand). Ensembl gene ENSG00000188833.
Subcellular location: Cell membrane
Subcellular location (Human Protein Atlas): Cytosol; Nucleoplasm; Vesicles
Pathways (Reactome):
Metabolism: Phosphate bond hydrolysis by NTPDase proteins
Gene Ontology:
Molecular function: ADP phosphatase activity; apyrase activity; ATP hydrolysis activity; nucleoside diphosphate phosphatase activity; ribonucleoside triphosphate phosphatase activity; UDP phosphatase activity; GDP phosphatase activity; hydrolase activity; pyrophosphatase activity
Biological process: ribonucleoside diphosphate catabolic process; ribonucleoside triphosphate catabolic process; nucleoside diphosphate catabolic process
Cellular component: plasma membrane; membrane
Genetic constraint (gnomAD): Loss-of-function variants: 35 observed, 46.9 expected, observed/expected ratio (o/e) 0.75, 90% interval 0.57 to 0.99. The upper end of that interval is the gene's LOEUF score, 0.99, which puts it in group 4 of 6, group 1 being the genes least tolerant of losing a copy. Missense variants: 647 observed, 636.54 expected, observed/expected ratio (o/e) 1.02, 90% interval 0.95 to 1.09. Synonymous variants: 297 observed, 283.67 expected, observed/expected ratio (o/e) 1.05, 90% interval 0.95 to 1.15.
Homologues: Orthologues: macaque ENTPD8 (95% identical), pig ENTPD8 (78% identical), rabbit ENTPD8 (78% identical), rat Entpd8 (75% identical), mouse Entpd8 (74% identical), dog ENTPD8 (74% identical), guinea pig ENTPD8 (74% identical), tropical clawed frog entpd8 (52% identical), chimpanzee ENTPD8 (51% identical), zebrafish entpd8 (45% identical). Paralogues in human: ENTPD2 (43% identical), ENTPD1 (42% identical), ENTPD3 (38% identical), ENTPD7 (26% identical), ENTPD4 (24% identical), ENTPD5 (23% identical), ENTPD6 (20% identical).
Diseases named in the same sentence as ENTPD8 in open-access papers:
ENTPD8 is named in the same sentence as 34 diseases in open-access papers, as found by Europe PMC text mining. Sharing a sentence is not in itself a finding about the gene and the disease. The quoted sentences say what the papers report.
pancreatic cancer (3 papers, 2020 to 2025). "ENTPD8 expression was lower in liver cancer, colorectal cancer, renal cancer, and gastric cancer compared to normal tissues, while it was higher in breast cancer, lung cancer, and pancreatic cancer, among others." (PMID 39995876, 2025).
asthma (1 paper, 2024). "Chelidonium majus relieved OVA-induced asthma in rats by regulating the Alox15, P4ha1, Pla2g16, Pde3a, Nme1, Entpd8 and Adcy9 genes expression to restore the disorders in energy metabolism and inflammation." (PMID 38671520, 2024).
colon cancer (1 paper, 2024). "Our analysis of CD39, ENTPD3 and ENTPD8 expression in colon cancer cell-derived exosomes revealed relatively low expression in both cell lysates and control cell-derived exosomes (ExoRKO−shNC and ExoDLD1−shNC)." (PMID 38755598, 2024). "In this study, for the first time, we performed a screen and demonstrated that ENTPD2 but not other ATPases (CD39, ENTPD3 and ENTPD8) is highly expressed in human colon cancer cells and is closely associated with poor patient prognosis." (PMID 38755598, 2024). "In 23 colon cancer tissues, the ENTPD2 level was higher than those of CD39 and ENTPD8." (PMID 38755598, 2024). "Here, we found for the first time that ENTPD2 is ubiquitously expressed in colon cancer cells, unlike other ATPases (CD39, ENTPD3 and ENTPD8)." (PMID 38755598, 2024).
colon tumor (1 paper, 2024). "Among the extracellular ENTPDases (CD39, ENTPD2, ENTPD3 and ENTPD8), ENTPD2 had the highest expression in colon tumor tissues, according to analysis of data in GEPIA2." (PMID 38755598, 2024).
epidermoid carcinoma (1 paper, 2025). "Fluorescence staining of ENTPD8 was also observed in human epidermoid carcinoma cell line A-431, human glioblastoma cell line U-251MG, and human osteosarcoma cell line U-2 OS." (PMID 39995876, 2025).
leukemia (1 paper, 2016). A malignant (clonal) hematologic disorder, involving hematopoietic stem cells and characterized by the presence of primitive or atypical myeloid or lymphoid cells in the bone marrow and the blood. "Through a CGH array analysis, we next extracted five candidate genes (GALNT2, DCHS2, ENTPD8, PNPLA7, FBXW7) involved in drug resistance in leukemia cells." (PMID 28025493, 2016).
liver cancer (1 paper, 2025). An epithelial or non-epithelial malignant neoplasm that arises from the liver. "Immunohistochemistry, The Cancer Genome Atlas (TCGA) data, and single-cell expression analysis revealed reduced ENTPD8 levels in liver cancer compared to adjacent tissues, with ENTPD8 primarily expressed in tumor cells within the tumor tissue." (PMID 39995876, 2025). "The results showed that as the grade of liver cancer increased, the expression of ENTPD8 decreased." (PMID 39995876, 2025). "Furthermore, using the TISCH database, we analyzed the expression of ENTPD8 in single-cell data from liver cancer datasets GSE125449, GSE146115, and GSE166635, revealing that ENTPD8 is primarily expressed in HCC cancer cells." (PMID 39995876, 2025).
rectal cancer (1 paper, 2025). A primary or metastatic malignant neoplasm that affects the rectum. "Additionally, another study suggests that ENTPD8 could serve as a potential prognostic risk indicator in rectal cancer." (PMID 39995876, 2025).
tumor (3 papers, 2025). "Subsequently, we used GTEx and UALCAN to analyze the expression of ENTPD8 in tumor tissues and normal tissues of different cancer types." (PMID 39995876, 2025). "At the single-cell level, ENTPD8 is primarily expressed in tumor cells of HCC." (PMID 39995876, 2025). "This suggests strong tumor specificity of ENTPD8 expression." (PMID 39995876, 2025). "The data showed a significant inhibition of tumor growth after overexpression of ENTPD8." (PMID 39995876, 2025). "Understanding the full extent of ENTPD8’s role in immune modulation and tumor progression could reveal additional therapeutic avenues and help to define its potential as a predictive biomarker for response to immunotherapy." (PMID 39995876, 2025). "We performed immunohistochemistry on tumor tissues and corresponding adjacent tissues from three patients with HCC, showing a significant downregulation of ENTPD8 expression in HCC." (PMID 39995876, 2025). "GO analysis showed that in the biological processes (BP) category, genes such as APOA1 and ENTPD8 were upregulated in MACCS1, suggesting a role for metabolic reprogramming in fueling tumor invasion and metastasis." (PMID 41037214, 2025). "The proteomic analyses revealed that the combination treatment significantly downregulated tumour-promoting genes such as HLA-F, TRIAP1, TMBIM6, and ENTPD8, suggesting reduced mitochondrial integrity and immune escape, thereby enhancing apoptotic susceptibility." (PMID 41516237, 2025). "Therefore, the anti-cancer effect of ENTPD8 is not dependent on miR-214-5p, and it can affect tumor immunity by regulating the expression of miR-214-5p, rather than directly through the anti-tumor effect of miR-214-5p." (PMID 39995876, 2025).
cancer (2 papers, 2018 to 2025). A tumor composed of atypical neoplastic, often pleomorphic cells that invade other tissues. "The identification of ENTPD8 as a therapeutic target also highlights the broader challenge in cancer immunotherapy: the need to identify reliable biomarkers and develop combination strategies that can overcome immune resistance." (PMID 39995876, 2025). "We found significant differences in ENTPD8 gene expression among different cancers." (PMID 39995876, 2025). "The low expression of ENTPD8 in HCC tissues and its association with the risk of death in patients with HCC suggest that ENTPD8 may be a potential anti-cancer target in HCC." (PMID 39995876, 2025). "Furthermore, it is important to explore whether ENTPD8’s effects are cancer type specific or if its therapeutic potential can be generalized to other malignancies." (PMID 39995876, 2025). "As the field of immuno-oncology continues to evolve, we anticipate that further research into the molecular mechanisms of ENTPD8, particularly its role in immune modulation, will play a critical part in optimizing the treatment strategies for HCC and potentially other cancers." (PMID 39995876, 2025).
ENTPD8 also shares sentences with these, for which no sentence is quoted: infection (3 papers); Hypertension (2); Arthritis (1); bladder cancer (1); breast carcinoma (1); colorectal cancer (1); degenerative diseases (1); dyslipidemia (1); esophageal cancer (1); gastric cancer (1); glioblastoma (1); head and neck squamous cell carcinoma (1); hepatocellular carcinoma (1); Ileitis (1); inflammatory bowel disease (1); lung carcinoma (1); malaria (1); melanoma (1); multiple sclerosis (1); non-small cell lung carcinoma (1); osteosarcoma (1); parasitemia (1); Parkinson disease (1); renal carcinoma (1).